PIEZO2 (piezo type mechanosensitive ion channel component 2)
Diseases named in the same sentence as PIEZO2 in open-access papers (continued):
Sharing a sentence is not in itself a finding about the gene and the disease.
tumor (continued). "PIEZO2-regulated vascular permeability and endothelial cell functions underscore PIEZO2 as a central hub that integrates mechanical signals, vascular homeostasis, and tumor progression." (PMID 41327436, 2025). "One study revealed that tumour growth was suppressed in a mouse glioma model post-subcutaneous implantation of Piezo2 knockdown GL261 cancer cells." (PMID 40527011, 2025). "Taken together, PIEZO2 exhibits context-dependent oncogenic or tumor-suppressive functions across different cancer types." (PMID 41327436, 2025). "Inhibition of PIEZO2 synergized with chemotherapy, leading to a marked reduction in tumor burden in preclinical MB models, underscoring its role in mediating treatment resistance." (PMID 41327436, 2025). "PIEZO2 has emerged as a critical regulator of tumor angiogenesis, and its knockdown shows promising effects on inhibiting tumor growth through antiangiogenic mechanisms." (PMID 41327436, 2025). "Mechanosensitive ion channel PIEZO2 translates microenvironmental forces into Ca2+-dependent signals that shape tumor behavior." (PMID 41327436, 2025). "Rather than functioning as a universal oncogenic driver or suppressor, PIEZO2 appears to act as a contextual modulator of mechanical signaling, integrating cellular tension cues with transcriptional programs that dictate tumor phenotype." (PMID 41327436, 2025). "The role of PIEZO2 as a mechanotransduction hub in immune homeostasis and tumor progression is an emerging area of research." (PMID 41327436, 2025). "Piezo2 knockdown decreased tumour vascular density, suggesting that Piezo2 has a key role in regulating tumour angiogenesis as well as tumour growth and is a potential anti-angiogenic therapeutic target." (PMID 40527011, 2025). "In MB, particularly within the SHH molecular subtype, PIEZO2 expression is markedly upregulated in tumor tissues." (PMID 41327436, 2025). "Across cancers, PIEZO2 exhibits context-dependent roles, with evidence for both pro- and anti-tumor functions, depending on tissue type, molecular subtype, disease stage, and stromal context." (PMID 41327436, 2025). "Emerging evidence has revealed that PIEZO2 orchestrates tumor angiogenesis through a multifaceted regulatory network, integrating mechanotransduction with canonical signaling pathways." (PMID 41327436, 2025). "Although we found stronger Piezo2 expression in benign breast tissue, we also detected a global tendency for more Piezo2 expression in the more proliferative neoplasms." (PMID 39001475, 2024). "Whereas tumor-specific Piezo2 knockout in SHH MBs disrupts the blood-tumor barrier, decreases the quiescence of Sox2+ MB cells, and enhances MB chemosensitivity." (PMID 38355808, 2024). "The second study indicated that Piezo2 expression is reduced in malignant cells, showing lesser expression as the tumor is more undifferentiated." (PMID 39001475, 2024). "Emerging evidence supports that various MSCs localized at brain tumors or the tumor‐caused edema are upregulated, including TRPC6, Piezo1, and Piezo2." (PMID 38923822, 2024). "And the expression of PIEZO2 is positively correlated with the gene expression of tumor progression and metastasis in GC." (PMID 38216574, 2024). "Piezo2 is known to regulate endothelial cell proliferation, migration, and tube formation in tumor vasculature, and the experimental knockdown of Piezo2 shows decreased angiogenesis, vascular hyperpermeability, and vascular leakage in tumor endothelial cells." (PMID 38054043, 2023). "In tumor tissues, Piezo2 promoter hypermethylation is significantly more frequent than in normal tissues and correlates with gender, differentiation, tumor (T) stage, lymph node metastasis, and clinical stage." (PMID 36837670, 2023). "Knockdown of the MB tumor cell‐specific Piezo2 gene disrupted the BTB by promoting the transduction of WNT/β‐catenin signaling." (PMID 37366640, 2023).
tumor (continued). "Piezo1 and Piezo2 participate in aberrant mechanical loading-induced apoptosis in chondrocytes, type II pneumocytes, and tumor cells." (PMID 37420255, 2023). "Piezo2 promotes a favorable tumor microenvironment with increased vascular density and leakage by inducing Ca2+-dependent Wnt/β-catenin signaling in endothelial cells." (PMID 36158191, 2022). "Knockout of the Piezo2 gene in tumor endothelial cells inhibited tumor growth by suppressing angiogenesis." (PMID 35701561, 2022). "The mRNA expression levels of Piezo2 in tumor tissues were higher than in normal tissues in CHOL, HNSC, KIRC, LIHC, PCPG, STAD, and THCA (p < 0.05)." (PMID 35991548, 2022). "On the contrary, Piezo2 expression levels in tumor tissues were lower than in normal tissues in BLCA, CESC, COAD, LUAD, etc.." (PMID 35991548, 2022). "So, there were complex interactions between Piezo2 and the anti-tumor or pro-tumor response of immune cells." (PMID 35991548, 2022). "Owing to the abnormal expression of Piezo2 in tumor tissues, we accessed the relationship between Piezo2 expression and the clinical staging of tumors." (PMID 35991548, 2022). "In gliomas, knocking down the expression of Piezo2 reduced the intracellular Ca2+ concentration, inhibited tumor angiogenesis and lowered vascular permeability through the Wnt/β-catenin pathway." (PMID 35701561, 2022). "In contrast, Piezo2 was down-regulated in tumor tissues from BLCA, COAD, GBM, KIRP, LUAD, LUSC, PRAD and READ." (PMID 35991548, 2022). "We found that Piezo2 was widely expressed in a wide variety of normal human tissues and tumor cell lines." (PMID 35991548, 2022). "Further analysis of protein expression of Piezo2 in tumors showed that Piezo2 protein was also expressed in various tumor tissues, including the cerebral cortex, kidney, stomach, etc." (PMID 35991548, 2022). "We sorted the expression levels of Piezo2 in tumor tissues and found that Piezo2 expression levels were the highest in MESO and lowest in CESC." (PMID 35991548, 2022). "Given that both Piezo1 and Piezo2 are upregulated in specific cancer cells and tissues, their potential use as tumor biomarkers for diagnosis and prognosis is indisputable." (PMID 32635333, 2020). "In NSCLC, knocking down both Piezo1 and Piezo2 by shRNA enhanced in vitro migratory capability and in vivo tumor growth." (PMID 32635333, 2020). "Although this mechanism remains to be confirmed in T-ECs, Piezo2 stands out as a crucial regulator of tumor angiogenesis and should be probed as a novel target for more effective anti-cancer treatments." (PMID 29324706, 2018). "It has been reported that the majority of the myelinated sensory neurons projecting to the bone marrow express PIEZO2 39, and that this gene plays an important role as a critical regulator of tumor angiogenesis and vascular permeability." (PMID 29030909, 2017). "To determine the effect of Piezo2 knockdown on tumor growth, we histologically examined the end-point tumors (day 28 after implantation)." (PMID 27329839, 2016). "We showed that Piezo2 knockdown in endothelial cells decreased tumor cell proliferation, migration, and invasion of tumor cells." (PMID 27329839, 2016). "Piezo2 was highly expressed in tumor endothelial cells, and its knockdown suppressed vascular leakage and tumor angiogenesis." (PMID 27329839, 2016). "At the end of experiment, tumor volume was reduced by 46% (P<0.01) in Piezo2 knockdown group compared to the control group, which was consistent with the reduction of tumor weight." (PMID 27329839, 2016). "Taken together, these studies provide the evidence for Piezo2 as a critical regulator of tumor angiogenesis and vascular permeability." (PMID 27329839, 2016). "By using TUNEL cell death detection assay, we found that tumor grown in a Piezo2-knockdown environment had more TUNEL-positive apoptotic cells." (PMID 27329839, 2016).
tumor (continued). "Tumor size was significantly reduced in Piezo2 shRNA transfected-group compared to scrambled shRNA transfected-group 2-week after tumor inoculation." (PMID 27329839, 2016). "In the present study, we revealed that Piezo2 was localized in the endothelial cells in tumor vasculature and its knockdown inhibited tumor angiogenesis, vascular leakage, and tumorigenesis." (PMID 27329839, 2016). "We showed that Piezo2 knockdown tumor had less vascular permeability compared with the control group." (PMID 27329839, 2016). "In conclusion, we demonstrated that Piezo2 knockdown led to tumor growth inhibition, reduced vascular density and vascular hyperpermeability." (PMID 27329839, 2016). "In vitro co-culture system was also conducted to determine the effect of Piezo2 knockdown in endothelial cells on tumor cell function." (PMID 27329839, 2016). "Tumor tissues from the mice implanted with Piezo2 knockdown GL261 cells showed decreased tumor vascular density and vascular leakage." (PMID 27329839, 2016). "We also infused Evans blue intravenously into mice bearing equal-sized tumors to determine the effect of Piezo2 knockdown on tumor vascular permeability." (PMID 27329839, 2016). "In particular, we highlight the potential of PIEZO2 as a combinatorial target al.ongside existing therapies—including anti-angiogenic regimens, chemo- and radiotherapy—and as a unique molecular interface linking tumor mechanobiology to cancer pain modulation." (PMID 41327436, 2025). "Furthermore, PIEZO2 ablation diminishes the quiescent phenotype of tumor cells, sensitizing them to chemotherapy by disrupting their dormancy-associated survival mechanisms." (PMID 41327436, 2025). "It is possible that PIEZO2-mediated mechanotransduction could contribute to tumor cell survival under therapeutic stress, suggesting that combined therapies targeting PIEZO2 and other key signaling pathways may provide increased therapeutic benefits." (PMID 41327436, 2025). "However, the roles of PIEZO2 in tumors are highly context dependent, presenting a paradoxical landscape in which it can either promote or inhibit tumor progression depending on the specific cellular and environmental context." (PMID 41327436, 2025). "For example, margaric acid (MA) and EPA have demonstrated therapeutic potential by suppressing PIEZO2 activity, thereby providing a possible means to inhibit PIEZO2-mediated oncogenic processes, including tumor cell proliferation, invasion, angiogenesis, and metastasis." (PMID 41327436, 2025). "The involvement of PIEZO2 in tumor progression and metastasis suggests that targeting PIEZO2 could be a promising strategy for inhibiting cancer spread, particularly for cancers characterized by abnormal mechanical properties and metastasis." (PMID 41327436, 2025). "Within the tumor vasculature, PIEZO2 is predominantly localized to endothelial cells, where it orchestrates critical angiogenic processes, including endothelial proliferation, migration, and tube formation, through its ability to transduce mechanical cues into intracellular Ca2+ signaling." (PMID 41327436, 2025). "Furthermore, the same study demonstrated that Piezo2 is localised in the endothelial cells that line tumour blood vessels, termed tumour endothelial cells." (PMID 40527011, 2025). "In the context of tumor progression, PIEZO2 acts as a multimodal mechano-regulatory hub." (PMID 41327436, 2025). "In this context, targeting the inhibition of PIEZO2 channels could represent a promising analgesic strategy for tumor treatment." (PMID 41327436, 2025). "Moreover, the MCF-7 cell line was also employed in the first study regarding Piezo2 expression, with opposite results to Piezo1 regarding the prognostic significance, suggesting a relationship between Piezo2 and the least aggressive neoplasms." (PMID 39001475, 2024).
tumor (continued). "The majority of cases were positive for Piezo2, with variable pattern and intensity, with score 8 being the most frequent category, with intense and either complete or nearly complete expression in the neoplasm." (PMID 39001475, 2024). "In gliomas, however, it is Piezo2 that supports tumor angiogenesis." (PMID 36837670, 2023). "These suggested that Piezo2 may exhibit opposite results targeting different immunotherapy checkpoints in different tumor environments." (PMID 35991548, 2022). "Due to the ion channel properties of Piezo2, we considered whether Piezo2 could affect downstream signaling and thereby involve in the progression and metastasis of the tumor." (PMID 35991548, 2022). "Furthermore, we assessed the mRNA expression levels of Piezo2 in various normal tissues, including the digestive system, nervous system, cardiovascular system, etc., and multiple human tumor cell lines." (PMID 35991548, 2022). "Our results showed associations between Piezo2 and CD4+ T memory cells, mast cells, and dendritic cells, suggesting that Piezo2 may involve in tumor progression by influencing immune infiltration or regulating immune cell function." (PMID 35991548, 2022). "Similarly, inoculation of A549 cells with stable transfection of sh-PIEZO2 also promoted tumor growth in nude mice, and these xenografts showed less expression of human PIEZO2 in comparison with mice inoculated with control cells." (PMID 30745454, 2019). "We then examined the effect of Piezo2 knockdown on tumor vascular architecture." (PMID 27329839, 2016). "Inspired by these findings, we speculated that Piezo2 is a potential regulator of tumor angiogenesis." (PMID 27329839, 2016). "We showed that Piezo2 knockdown suppressed tumor angiogenesis and vascular permeability in vivo." (PMID 27329839, 2016). "One possible mechanism which Piezo2 knockdown may inhibit tumor growth is by direct anti-angiogenic effects (i.e., by inhibiting endothelial cell proliferation, migration, and tube formation)." (PMID 27329839, 2016). "PIEZO2 has a negative correlation with cell stemness and mutation levels in patients with GC and a positive correlation with immune cell infiltration and gene expression in the tumor microenvironment." (PMID 38216574, 2024). "The increased expression described in aggressive vesical neoplasms, high-grade gliomas, and others may be more complex to explain; in this regard, it has been suggested that Piezo2 activation accelerates the cell cycle through activation of Akt/mTOR, enhancing the growth of the neoplasm." (PMID 39001475, 2024). "There was no apparent association between Piezo2 expression and tumor size in different tumors." (PMID 35991548, 2022). "However, Piezo2 was recognized as representing a double-edged sword in terms of tumor growth." (PMID 35991548, 2022). "Thus, Piezo2 may play both cancer-promoting or cancer-suppressing functions in different tumor types." (PMID 35991548, 2022). "Piezo2 intervene could suppresses tumor expansion by a concomitant decrease in tumor vascularity." (PMID 27329839, 2016). "We first determined whether Piezo2 knockdown affects tumor growth in vivo." (PMID 27329839, 2016). "Thus, Piezo2 is a potential therapeutic target for tumor angiogenesis." (PMID 27329839, 2016). "PIEZO2, a member of the PIEZO family of mechanically activated ion channels, is expressed in tumor cells and stromal cells within tumors." (PMID 41327436, 2025). "Using double immunohistochemistry for PIEZO2 and CK20, PIEZO2 and ChrA, or PIEZO2 and NFP, we observed co-localization of those proteins in a variable proportion of cells within the tumor mass." (PMID 35743679, 2022). "Knockdown of PIEZO1 or PIEZO2 in NSCLC cells significantly promoted cell migration in vitro and tumor growth in vivo." (PMID 30745454, 2019). "Piezo2 knockdown decreased VEGF- or IL-1β-mediated pathological angiogenesis, implying that Piezo2 plays an anti-angiogenic role during tumor growth." (PMID 27329839, 2016).
tumor (continued). "The modified Miles assay revealed that Piezo2 knockdown decreased VEGF- and IL-1β-mediated vascular leak, suggesting that Piezo2 plays an anti-permeability role during tumor angiogenesis." (PMID 27329839, 2016). "In NSCLC, the expression of PIEZO2 is significantly reduced in tumor tissues compared with adjacent non-cancerous tissues." (PMID 41327436, 2025). "As ECM stiffness generally regulates tumor progression through its receptors, we systematically screened several common ECM-sensing receptors (ITGB1, CD44, Piezo1, Piezo2, YAP1, Syndecan1, and DDR1) via siRNA knockdown, and confirmed the knockdown efficiency by conducting qRT-PCR analyses." (PMID 40685383, 2025). "In the same study, the Piezo2 knockout also reversed detrimental WNT/β-catenin signalling states, reduced cancer cell quiescence, and enhanced chemotherapy response, implying that inhibition of Piezo2 may address BTB integrity and tumour quiescence." (PMID 40527011, 2025). "In pancreatic cancer, PIEZO2 expression is markedly elevated in tumor tissues compared with adjacent non-tumorous counterparts." (PMID 41327436, 2025). "By linking mechanistic discoveries to therapeutic implications, this work aims to define PIEZO2 not merely as a passive mechanosensor, but as a context-aware and targetable nexus in tumor progression and therapy." (PMID 41327436, 2025). "It has been recently reported that knockout of Piezo2 in SOX2+ medulloblastoma cells reduces local tissue stiffness, improves drug delivery across the blood-tumor barrier, and increases survival by altering WNT/β-catenin signaling between tumor and endothelial cells." (PMID 37762011, 2023). "Knockout of Piezo2 resulted in a compromised BBTB, as shown by intratumoural accumulation of systemically administered 1kDa Cadaverine and 70kDa Dextran, and extended survival in response to etoposide treatment compared to tumor-bearing controls." (PMID 36776301, 2023). "There was no statistical difference in tumor weight, although the PIEZO2 overexpressed group trended to be slightly heavier." (PMID 36077309, 2022). "Given the critical role of Piezo2 in tumor angiogenesis and vascular hyperpermeability, it is not surprised that Piezo2 is a potential target for anti-angiogenic therapy during tumor treatment." (PMID 27329839, 2016). "However, despite this regulatory role, genetic ablation of PIEZO2 does not markedly alter MB proliferative output, implying compensatory pathways maintain tumor growth control." (PMID 41327436, 2025). "Likewise, the tumor cells lacked expression of the common PNEC mechanosensor PIEZO2 but showed broad expression of the acid-sensitive channel KCNK3 and opsin OPN1SW, which is expressed only by rare normal PNECs." (PMID 36469459, 2022). "However, the expression and function of Piezo2 in tumor angiogenesis has not been elucidated." (PMID 27329839, 2016). "the activated Piezo2 triggers endothelial WNT/β‐catenin pathway but not those in medulloblastoma Sox2+ cells, which wraps the local capillaries to form the blood‐tumor barriers." (PMID 38923822, 2024). "Although there was no statistical difference in the down-regulation of Piezo2 in tumor tissues of BRCA in our study, its gene activity was significantly reduced in tumor tissues." (PMID 35991548, 2022). "Piezo2 (green fluorescence) was found to be mainly expressed in tumor endothelial cells (labeled by CD31, red fluorescence) in wild-type mice but not Piezo2 knockdown mice." (PMID 27329839, 2016).